RNU6-201P (RNA, U6 small nuclear 201, pseudogene)
Gene: Small nuclear RNA gene on chromosome 22 (31,837,238 to 31,837,298, forward strand). Ensembl gene ENSG00000252909.
Homologues: Orthologues: rabbit U6 (72% identical), guinea pig U6 (70% identical). Paralogues in human: RNU6-33P (92% identical), RNU6-774P (92% identical), RNU6-893P (92% identical), RNU6-1 (90% identical), RNU6-1029P (90% identical), RNU6-116P (90% identical), RNU6-11P (90% identical), RNU6-12P (90% identical), RNU6-1309P (90% identical), RNU6-13P (90% identical), RNU6-17P (90% identical), RNU6-18P (90% identical), and 1282 more.